FGF2 (fibroblast growth factor 2)
Diseases named in the same sentence as FGF2 in open-access papers (continued):
Sharing a sentence is not in itself a finding about the gene and the disease.
metabolic disorders (2 papers, 2020 to 2025). "We also observed up‐regulation of FGF2, 13 and 14 in patients with increased FGF21 expression, and this broadens the perspective of FGFs in metabolic disorders." (PMID 39962359, 2025).
skeletal dysplasia (2 papers, 2013 to 2018). Any Mendelian diseases that affects growth and development of the skeleton. "Genetic studies in animals and etiology of human skeletal dysplasias showed that FGF2 overexpression as well as mutation of FGF2 or the corresponding receptors cause bone abnormalities." (PMID 29556234, 2018).
FGF2 also shares sentences with these, for which no sentence is quoted: infarction (9 papers); cerebral infarction (7); liver disease (7); breast (6); gastric ulcer (6); preeclampsia (6); renal cell carcinoma (6); vascular tumors (6); acute myocardial infarction (5); lymphedema (5); retinal ischemia (5); Skin ulcer (5); acne (4); chronic hepatitis (4); chronic periodontitis (4); embryonal carcinoma (4); gastrointestinal stromal tumor (4); head and neck cancer (4); peripheral vascular disease (4); proliferative diabetic retinopathy (4); Thrombocytopenia (4); type 1 diabetic (4); acute lung injury (3); allergic reaction (3); amyotrophic lateral sclerosis (3); benign tumours (3); bladder tumor (3); cataract (3); diabetic neuropathy (3); dyslipidemia (3).
A further 278 diseases each share a sentence with FGF2 in 3 papers or fewer.